STAT3 (signal transducer and activator of transcription 3)
Diseases named in the same sentence as STAT3 in open-access papers (continued):
Sharing a sentence is not in itself a finding about the gene and the disease.
tumor (continued). "In rat tumor models generated with the STAT3 S727A variant expressing tumor cell line were more aggressive, leading to the assumption that the CK2-PPA2 pathway regulates STAT3 Ser727 phosphorylation and herein tumorigenicity." (PMID 36009534, 2022). "The p-Stat3 protein expression in tumor tissue was associated with differentiation(r = 0.158, P<0.05), T stage(r = 0.184, P<0.05), N stage(r = 0.313, P<0.01) and TNM staging (r = 0.276, P<0.01)." (PMID 36454780, 2022). "As a key mediator of tumor-associated immune tolerance, STAT3 has been reported to be critical for the modulation of immune cells within TME in CRC, as outlined by many studies." (PMID 34976223, 2022). "STAT1 and STAT3 were selected, as these two transcription factors are known to play prominent roles in tumorigenesis and tumor-associated immunosuppression." (PMID 35382852, 2022). "STAT3 signaling in mouse glioma tumor-associated myeloid progenitor cells induces S100A8 and S100A9, which are inflammatory factors that arrest myeloid cell maturation, including DCs." (PMID 35711434, 2022). "One contender is STAT3, a transcription factor that is associated with K-ras mutations and aids tumor development and progression through tumor cell intrinsic and extrinsic mechanisms." (PMID 35406557, 2022). "STAT3 is linked to tumor growth and survival, as evidenced by STAT3 hyperactivation in several cancer types and as a poor prognosis marker." (PMID 36230990, 2022). "Critical growth factors and cytokines, including IL-6, IL-11, IL-22, HGF, and EGF, in addition to oncogenic tyrosine kinases such as c-Met and Src, cause STAT3 dependent activation of tumor growth." (PMID 35327456, 2022). "Taken together, there is a vast array of evidence demonstrating STAT3 as a pro-tumorigenic transcription factor implicated in many independent aspects of tumor biology." (PMID 35053592, 2022). "CD163+ tumor-associated macrophages can secrete IL-6 to activate tumor cells JAK2/STAT3, promoting EMT and CTC-mediated metastasis, which is closely related to poor prognosis of patients." (PMID 36568117, 2022). "Further, S1PR1 promotes STAT3 activation in CD4+ T‐cell associated with Tregs accumulation at tumor sites." (PMID 35356799, 2022). "STAT3 is deemed as a pivotal regulator of tumor metastasis because its target genes are implicated in multiple steps of tumor metastasis including cell invasion, migration." (PMID 36531027, 2022). "STAT3 signaling plays a key role in mediating Warburg effect, which is beneficial to the survival of tumor cells in the TME with nutritional deficiency." (PMID 35062950, 2022). "Multiple studies have proven that increased phosphorylated STAT3 (pSTAT3) is usually associated with cell proliferation, invasion, and angiogenesis, leading to tumor progression, metastasis, drug resistance, and immune escape." (PMID 36559280, 2022). "A robust in vivo xenograft model of STAT3-deficient tumor cell lines with adoptive transfer of human primary NK cells would be necessary to further elucidate the impact of STAT3 on NKG2D-mediated NK-cell surveillance." (PMID 35865518, 2022). "STAT3 activation helps to promote tumor progression and is associated with PDAC through PDAC patients’ biopsy study." (PMID 35433829, 2022). "One such example is SD-36, a small-molecule inhibitor of STAT3 which results in its degradation and is able to cause strong regression of in vivo tumor growth in mouse leukemia and lymphoma models." (PMID 35053592, 2022). "High levels of IL6 were supposed to promote tumor development, and activation of the downstream pathway JAK/STAT3 was commonly associated with increased tumor burden." (PMID 35692503, 2022). "IL-6-mediated STAT3 activation in the tumor microenvironment and cancer cells is associated with tumor cell proliferation, angiogenesis and metastasis." (PMID 35844550, 2022).
tumor (continued). "Periostin-deficient MDSCs displayed reduced activation of ERK, AKT and STAT3 and periostin deficiency decreased the immunosuppressive functions of MDSCs during tumor progression." (PMID 35719975, 2022). "Tumor differentiation, pN, and high expression of p-STAT3 are independent risk factors for 5-year survival in patients with AEG." (PMID 36225196, 2022). "Among them, STAT3 is the most well-studied and is broadly hyperactivated in a variety of cancers and closely associated with tumor cell proliferation and metastasis." (PMID 35216314, 2022). "Through Western blot analysis of tumor tissues, we found that liensinine treatment significantly downregulated the expressions of p-STAT3 and p-JAK2, thereby causing a significant reduction in the ratio of p-STAT3/STAT3 and p-JAK2/JAK2." (PMID 35116094, 2022). "STAT3 is mainly expressed in naive CD4+ T cells and activated p-STAT3 can modulate the transcriptional activity of target genes associated with tumor cell migration and invasion." (PMID 36437827, 2022). "Collectively, IL-6 is considered to be a pivotal tumor promoter in colitis-associated cancer and STAT3 is essential for the transduction of tumor-promoting signals from IL-6." (PMID 36135048, 2022). "SMAR1 represses the transcription of STAT3, hence shifting tumor‐associated macrophages toward an anticancer M1 profile." (PMID 34689394, 2022). "Excessive STAT3 activation, fuelled and maintained by tumor-associated IL-11 expression, appears to be sufficient to trigger neoplastic behaviour of gastric epithelium without the requirement for additional predisposing genetic alterations." (PMID 35844493, 2022). "Consistently, Smad7 mRNA and protein expression were significantly reduced in xenografts that were generated by the inoculation of Stat3-deficient tumor cells into BALB/cnu/nu mice." (PMID 36291778, 2022). "Hereby, immune cell specific SGPL1 ablation caused massive immune cell infiltration, delayed tumor formation, and a mix between the previously observed STAT3 pattern and immunosuppressive marker expression." (PMID 35163211, 2022). "Further underlining the importance of STAT3, several studies revealed that STAT3 inhibition dampened MDSCs in the tumor microenvironment and proved to be a useful anticancer therapy." (PMID 36110844, 2022). "The elevated gene transcription of MMP‐9 was demonstrated to be associated with activation of the STAT3 in tumor‐associated myeloid cells." (PMID 35356799, 2022). "Various cell types in the TME of cancers release IL-6, leading to the activation of the IL-6/JAK/STAT3 pathway in both tumour cells and tumour-associated immune cells, which in turn promotes tumour cell proliferation, invasiveness and metastasis." (PMID 36555253, 2022). "Platinum-induced secretion of IL-6 from cancer-associated fibroblasts in the tumor microenvironment promotes the enrichment of OCSC in residual tumors after chemotherapy through activation of STAT3 and up-regulation of ALDH1A1 expression." (PMID 36387165, 2022). "The signal transducer and activator of transcription 3 (Stat3) can be activated by IL-6 through phosphorylation and plays a crucial role in carcinogenesis through tumor-associated immunosuppression." (PMID 36454780, 2022). "STAT3 also contributes to cancer cachexia by enhancing tumorigenesis, metastasis and immunosuppression, particularly in tumor types associated with a high risk of cachexia." (PMID 36091226, 2022). "STAT3 and STAT6 have been linked to M2 polarization in tumor progression, although there are studies that demonstrate that the specific loss of myeloid STAT3 activity enhances cancer progression." (PMID 35053592, 2022). "JAK2/STAT3 can induce systemic inflammatory response and is associated with the occurrence of tumor cachexia." (PMID 36591515, 2022). "The 5-year survival rate for AEG patients was 41.0% and was significantly associated with tumor differentiation, pN, pTNM, and p-STAT3 (P < 0.05, P < 0.01, P < 0.05, P < 0.01)." (PMID 36225196, 2022).
tumor (continued). "Many studies have shown that the dysregulation of EGFR signaling pathways including AKT, ERK and STAT3 is associated with tumor proliferation and survival." (PMID 35572726, 2022). "For example, Yang and colleagues elucidated that tumor-associated B lymphocytes with activated STAT3 resulted in the accelerated tumor progression by virtue of augmenting tumor angiogenesis." (PMID 36439137, 2022). "On the other hand, Stat3 is a crucial mediator of carcinogenesis through tumor-associated immunosuppression, implying a key role in tumor cell proliferation, invasion, metastasis, and immune escape." (PMID 36454780, 2022). "Continuous activation of STAT3 in tumor-associated immune cells activates the expression of downstream genes VEGF, IL-10 and IL-6, and causes the proliferation of tumor-infiltrating hematopoietic stem cells, which ultimately leads to poor prognosis." (PMID 36561336, 2022). "In many publications, the association between STAT3 and tumor growth and immune evasion has been clearly documented." (PMID 36176415, 2022). "Given the difficulties in targeting K-ras driver mutations, tumor-promoting inflammation and the STAT3 pathway are gaining attention as therapeutic targets." (PMID 35406557, 2022). "After being polarized, tumor-associated macrophages (TAMs) secrete IL-6, which binds to its receptor on CSCs and activates the STAT3 pathway, promoting CSC expansion and activation of the expression of stem-related genes, such as Sox-2, Oct-3/4 and Nanog." (PMID 36497411, 2022). "STAT3 activation is associated with high expression of tumor promoting cytokines and growth factors such as IL-10, transforming growth factor (TGF)-β and vascular endothelial growth factor (VEGF)-A." (PMID 35865518, 2022). "By regulating the signal transducer and activating the STAT3 transcription signaling pathway, which is linked to tumor progression, this combination can negatively regulate the cell cycle and activate apoptosis." (PMID 36193062, 2022). "Aberrant STAT3 activation has been implicated in tumor initiation and progression, and preclinical evidence strongly supports STAT3 as a potential treatment target in STAT3-dependent epithelial cancer." (PMID 36509291, 2022). "STAT3 blockade also can revert DC immunosuppression by inducing maturation, thus is associated with an increase in tumor infiltrating CD4+ and CD8+ T cells and a decrease in T regulatory cells." (PMID 36230990, 2022). "We have observed that IL-6, Stat3, PD-1 and PD-L1 are associated not only within the signaling pathways but also with multiple immune cells and tumor microenvironment." (PMID 36454780, 2022). "A positive feedback loop in GSCs has also been discovered, in which Toll-like receptor 9, a molecule associated with tumor growth, drives activation of STAT3, which in turn upregulates expression of the Toll-like receptor." (PMID 35954407, 2022). "Cancer is a complex multifactorial disease mediated by multiple signaling pathways that regulate the expression of a wide array of genes implicated in tumor initiation, progression and metastasis, including the STAT3 signaling pathway." (PMID 36299882, 2022). "Phosphorylation of STAT3, which was linked to greater tumor size and increased recurrence, was also elevated in HCC patients with poorer prognosis." (PMID 36232407, 2022). "In colitis associated colorectal cancer and hepatocellular carcinoma, tumor promotion is supported by IL-6 in a STAT3-dependent signaling mechanism." (PMID 35327456, 2022). "Multivariate analysis showed that tumor size and p-STAT3 expression were associated with RFS, whereas positive p-STAT3 expression was significantly associated with a shorter RFS for ER(−) patients." (PMID 35314590, 2022).
tumor (continued). "The MSCs suppress tumour growth by inhibiting the signalling pathways associated with proliferation (e.g., STAT3, AKT, PI3K, and Wnt signalling pathways), cell cycle progression, the inhibition of apoptosis, and the suppression of angiogenesis." (PMID 35954425, 2022). "Proteogenomic integration analysis indicated that SND1 and CDK5 amplifications on chromosome 7q were associated with the activation of STAT3, which was relevant to tumor proliferation." (PMID 35659036, 2022). "TQ is associated with many pathways and stimulated apoptosis in tumor cells via inhibiting the STAT3 pathway by inhibiting JAK2- and Src-induced phosphorylation of EGFR-TK." (PMID 35402265, 2022). "STAT3 was also activated in tumor-associated immune cells to induce the expression of immune suppression related genes and contribute to immunosuppression in OSCC tumor microenvironment (TME)." (PMID 36231093, 2022). "In many cancers, excessive activation of IL-6/JAK/STAT3 is associated with tumor cell proliferation, migration, invasion and inhibition of antitumor immune responses, and is associated with poor tumor prognosis." (PMID 35359408, 2022). "We review the mechanisms of STAT3 pathway regulation and the consequent cancer hallmarks associated with tumor biology that are induced by the STAT3 pathway." (PMID 35356799, 2022). "It is reported that aberrant STAT3 activation in tumor cells is associated with cell proliferation, cell survival, invasion, angiogenesis, and metastasis." (PMID 36014573, 2022). "Persistently activated STAT3 is associated with the proliferation, survival, and invasiveness of tumor cells, including those of breast, lung, pancreatic, and head and neck origin." (PMID 36014573, 2022). "Studies reported that elevated activity of signal transducer and activator of transcription 3 (STAT3) is positively associated with tumor progression." (PMID 36003395, 2022). "C4_CD8, which was composed of cells mainly from tumor and normal adjacent kidney tissues, was associated with high activity of TFs involved in cytokine responses such as STAT3 and STAT5B." (PMID 35668194, 2022). "Activation and amplification of the signal transducer and activator of transcription 3 (STAT3) protein has been reported in nearly half of all human tumors and is associated with tumor proliferation, tumor survival, tissue invasion, and immunosuppression." (PMID 35954407, 2022). "STAT3 is often over-activated in various cancers and is associated with tumor immunosuppression and poor prognosis." (PMID 35799780, 2022). "High phospho-STAT3 levels were associated with lower risk of early recurrence, lower rates of distant metastases, lower histological grade, smaller tumor size and overall better prognosis." (PMID 35053592, 2022). "The tumor-promoting effect of IL-6 largely depends upon STAT3 activation; IL-6-deficient mice have reduced tumor growth and have abrogated STAT3 activation, suggesting the importance of IL-6 and STAT3 signaling in promoting colorectal tumorigenesis." (PMID 35205671, 2022). "The expansion of myeloid-derived suppressor cells (MDSCs) in the tumor microenvironment is mediated by STAT3 and the differentiation of tumor-associated macrophages (TAMs)." (PMID 35053592, 2022). "CAFs-derived IL-6 participated in the activation of STAT3 signal in tumor‐associated neutrophils (TANs), which sustained the survival and function of TANs and inhibited T cell’s attack ability via the PD1/PD-L1 signaling." (PMID 36324128, 2022). "The aim of this study is to investigate the effects of resistance exercise training on inflammatory cytokines and oxidative-mediated STAT3 activation and muscle loss prevention in tumor-bearing mice." (PMID 35847939, 2022). "Cox regression analysis confirmed that tumor differentiation, pN, and high expression of p-STAT3 were independent risk factors for the 5-year survival rate in patients with AEG (P < 0.05, P < 0.01, P < 0.05)." (PMID 36225196, 2022).
tumor (continued). "Cox regression analysis confirmed that tumor differentiation, pN, and high expression of p-STAT3 were independent risk factors for the 5-year survival rate in patients with AEG." (PMID 36225196, 2022). "It is indicated that EMT suppression succeeds through blocking the expression of PD-L1 and the activation of STAT3, which are associated with tumor metastasis." (PMID 36358747, 2022). "STAT3 mutations have been rarely detected in other tumor types studied, thus it can be used as molecular markers for LGLL diagnosis and can provide a novel therapeutic target for patients with LGLL." (PMID 35600388, 2022). "The inhibition of the JAK2/STAT3 pathway in OC results in a loss of cancer stemness and reduced tumor growth." (PMID 35269636, 2022). "Resistance to anoikis is a primary characteristic of tumor cells that metastasize, and STAT3 is closely associated with anoikis resistance in NPC." (PMID 36313702, 2022). "It is possible that DNM3 mutations promote tumor cell growth through the activation of the c-MET/STAT3 pathway." (PMID 36528667, 2022). "For example, IL-6-ablated mice and STAT3-deficient mice exposed to azoxymethane (AOM)/DSS exhibited reduced tumor numbers, size and proliferation." (PMID 36135048, 2022). "Estrogen has been observed to exert protective effects against HCC development through interleukin 6 (IL-6) suppression, signal transducer and activator of transcription-3 (STAT3) inactivation, and tumor-associated macrophage inhibition." (PMID 35862398, 2022). "This study aimed to investigate the effects of RT on STAT3 activation by increased inflammatory cytokines and oxidative damage during tumor-induced muscle atrophy and strength loss." (PMID 35847939, 2022). "STAT3 activation in the tumor stroma is associated with impaired tumor immune surveillance of NK and CD8+ T cells." (PMID 35244291, 2022). "Studies also revealed that tumor environment-associated factors activate STAT3 and C/EBPb to increase the transcription of miR-21a, miR-21b, and miR-181b." (PMID 35634311, 2022). "Activation of STAT3 has previously been implicated in the regulation of cell plasticity, tumor cell invasion, and metastases." (PMID 35993361, 2022). "Studies in human tumor cell lines have previously shown that the tumor-associated overexpression of EGFR results in the sustained hyperactivation of Stat3, which eventually induces Smad7 expression." (PMID 36291778, 2022). "In these mice, the anti-metastatic responses observed in tumor-bearing mice with Stat3-deficient hematopoietic cells, correlated to the enhanced function of dendritic cells, T cells, natural killer (NK) cells and neutrophils." (PMID 35053592, 2022). "EGFR mutations cause abnormal activation of the downstream JAK/STAT3 signalling pathway, leading to increased expression of phosphorylated STAT3, followed by abnormal tumor growth, angiogenesis, invasion, and metastasis." (PMID 36185620, 2022). "This process causes their differentiation into an M2-like pro-tumor/anti-inflammatory phenotype through the signal transducer and activator of transcription 3 (STAT3)-dependent fatty acid oxidation mechanism." (PMID 35159208, 2022). "Collectively, these data suggest that inhibition of STAT3 suppresses IL20RB-induced tumor proliferation in bone and reduces the risk of bone metastasis." (PMID 36006737, 2022). "STAT3 inhibition reshapes the tumour immune microenvironment, but the underlying mechanisms have not been fully clarified." (PMID 35665592, 2022). "ARH-I can sequester STAT3, which mediates IL-6-transcriptional effects associated with tumor aggressiveness." (PMID 35565270, 2022). "The cell energy phenotype change in tumor cells caused cancer progression and resistance to chemotherapeutics; which were specifically related to up-regulated phosphorylated STAT3 protein expression levels." (PMID 36033954, 2022).